NRP1 (neuropilin 1)
Diseases named in the same sentence as NRP1 in open-access papers (continued):
Sharing a sentence is not in itself a finding about the gene and the disease.
colitis (4 papers, 2021 to 2025). Inflammation of the colon. "However, Nrp-1+iTreg almost completely suppressed the onset and progression of colitis including weight loss and intestine inflammation pathology with a significantly better effect than Nrp-1-iTreg (–C)." (PMID 35603221, 2022). "In future research, we plan to utilize both global and conditional knockout models of the TIGIT/NRP1 genes in mice, including specific T cell populations, to induce colitis and develop cellular models of UC." (PMID 41465029, 2025). "Collectively, these results suggest that CUR ameliorates experimental colitis by targeting the TIGIT/NRP1 axis, modulating gene and protein expression, and promoting an anti-inflammatory cytokine environment." (PMID 41465029, 2025). "It has been shown that NRP1 modulates and enhances the capacity of ILC3s to produce the pro-inflammatory cytokine IL-17A, thereby directly promoting and exacerbating colitis." (PMID 41465029, 2025). "Nrp-1+iTreg and Nrp-1-iTreg were adoptively transferred into a T cell-mediated colitis model to determine their ability to suppress inflammation." (PMID 35603221, 2022). "Consistently, Nrp-1+iTreg had a more potent ability to suppress Th1/Th17 cells in colitis." (PMID 35603221, 2022). "Nrp-1+iTreg could completely prevent colitis development, while Nrp-1-iTreg exerted only half control of colitis disease." (PMID 35603221, 2022). "In DSS-induced colitis, THC or THC+CBD treatments reduce polyps in colon cancer-induced mice and increase CD103+ dendritic cells and CD4+Nrp1+FoxP3+ T regulatory cells (nTregs) in the lamina propria through activation of the CB2 receptor." (PMID 34298921, 2021). "The increase in the ratio of CD4+Nrp1+FoxP3+ cells in the lamina propria reduces disease severity in THC- and THC+CBD-treated colitis mice compared to VEH-treated colitis mice." (PMID 34298921, 2021). "Notably, TIGIT/NRP1 knockout or knock-in mouse models were not employed to induce DSS-induced colitis, and the bioavailability of CUR in colonic mucosa and lymphoid tissues was not assessed." (PMID 41465029, 2025).
depression (4 papers, 2019 to 2023). "Nrp1 is upregulated in the post-mortem prefrontal cortex of individuals suffering from the MDD and has been proposed to be associated with neuronal morphological alterations in depression and related neuropsychiatric disorders." (PMID 31440139, 2019).
diabetic macular edema (4 papers, 2017 to 2025). "NRP1 has been implicated in diseases characterized by deregulated vasculature such as cancer, and in diseases of the retina such as proliferative diabetic retinopathy, diabetic macular edema and retinopathy of prematurity." (PMID 33876574, 2021). "SEMA3A levels have been reported to be significantly elevated in the vitreous fluid of patients with diabetic macular edema and proliferative diabetic retinopathy (PDR) via NRP1." (PMID 34248841, 2021). "An alternative strategy to prevent ocular vessel leakage may involve targeting both VEGF164 and SEMA3A signaling via NRP1, in particular in conditions where SEMA3A exacerbates VEGF-induced leakage, as has been proposed for the early phase of diabetic macular edema." (PMID 28289053, 2017).
endometriosis (4 papers, 2015 to 2025). The growth of functional endometrial tissue in anatomic sites outside the uterine body. "It was found that NRP-1 levels were elevated in cases of stage 2–4 endometriosis compared to the control group." (PMID 40507480, 2025). "The deregulation of epinephrine and semaphoring/NRP1 signaling pathways in the nerve cells of endometriosis lesion has been shown to support macrophage polarization." (PMID 34439896, 2021). "Sema 3A, NRP-1 and Plexin A1 immunostaining were found 100% of peritoneal and deep infiltrating endometriosis samples." (PMID 26720585, 2015). "In addition, another study showed that Sema3A can recruit Mφ through the Sema3A/Nrp-1 (Neuropilin-1) signaling pathway, guiding them to a hypoxic environment like endometriosis lesions." (PMID 34639133, 2021). "Although we did not have endometriosis and adenomyosis patients in our patient and control group, there are studies on NRP-1 levels in endometriosis and adenomyosis due to the presence of angiogenesis in the etiopathology." (PMID 40507480, 2025). "The expression of both NRP-1 and Plexin A1 in glandular epithelial cells of peritoneal endometriosis were also higher than that from eutopic endometrium of women with endometriosis as well as women without endometriosis (all the p values were less than 0.001)." (PMID 26720585, 2015).
experimental autoimmune encephalomyelitis (4 papers, 2013 to 2022). An autoimmune demyelinating disease of the central nervous system that is produced experimentally in animals by the injection of homogenized brain or spinal cord in Freund's adjuvant. "The cross talk between tuftsin and neuropilin-1 showed that tuftsin targeting neuropilin-1microglia and trigger the cells and promoting the M2 anti-inflammatory phenotype, and attenuate experimental autoimmune encephalomyelitis (EAE)." (PMID 30089122, 2018). "Additionally, lack of NRP-1 on surface of Tregs has been linked with impaired Treg suppressive function and worsening of experimental autoimmune encephalomyelitis severity." (PMID 36157881, 2022).
fibrosis (4 papers, 2020 to 2025). the formation of excess fibrous connective tissue in an organ or tissue in a reparative or reactive process. "Here, we investigated the impact of NRP1 on the progression of renal injury and fibrosis." (PMID 38977708, 2024). "Hepatocyte-specific NRP-1 knockout in CCl4- and NASH-induced fibrosis models reduced fibrosis severity, collagen deposition, and angiogenesis, along with lower TGF-β and VEGF secretion." (PMID 40419692, 2025).
kidney (4 papers, 2010 to 2026). "We verified that NRP1 siRNA transfection did not affect NRP2 expression and NRP2 siRNA transfection did not silence NRP1 expression in both lung A549 and kidney ACHN carcinoma cells." (PMID 20087344, 2010).
meningioma (4 papers, 2013 to 2023). A generally slow growing tumor attached to the dura mater. "Heterogenous expression of NRP1 was observed in an immunohistochemical analysis performed in tissue microarrays of 232 cranial meningioma specimens from 147 patients, including recurrent tumors." (PMID 37894289, 2023). "Immunohistochemical analysis of NRP1 expression in a series of 48 cases of meningiomas with different types and histological grades showed NRP1 staining in the vessels within all but two tumors and in the neoplastic cells in eighteen tumors." (PMID 37894289, 2023). "Genes related to angiogenesis and vascular permeability pathways had also significant matches, and at least one of them (NRP1) has been studied before in meningioma." (PMID 25003081, 2014). "In our study, we investigated VEGF-A, the receptors VEGFR-1-3 and their major co-receptors NRP-1 and NRP-2 in a cohort of 147 WHO grade II and III meningioma patients in order to elaborate potential therapeutic targets." (PMID 33528717, 2021). "We aimed to evaluate protein levels of vascular endothelial growth factor (VEGF)-A with the VEGF-receptors 1-3 and the co-receptors Neuropilin (NRP)-1 and -2 in WHO grade II and III meningiomas to elucidate the rationale for targeted treatments." (PMID 33528717, 2021). "To our knowledge, we are the first group reporting on NRP-1 and NRP-2 protein levels in WHO grade II and III meningiomas." (PMID 33528717, 2021). "NRP1 mRNA levels are higher in angiomatous compared to non-angiomatous meningiomas, whereas NRP1 protein levels are lower in angiomatous meningiomas." (PMID 37894289, 2023). "The aim of our study was to comprehensively analyze and evaluate protein expression levels of the VEGF-A-driven system with VEGFR-1-3 as well as the co-receptors NRP-1 and -2 in WHO grade II and III meningiomas in order to elucidate the rationale for adjuvant treatment targets." (PMID 33528717, 2021). "The major co-receptor of VEGFR-1 and VEGFR-2, Neuropilin-1 (NRP-1), has only been investigated in angiomatous meningiomas on an mRNA level so far while there is a lack of data on higher grade meningiomas." (PMID 33528717, 2021).
myocardial infarction (4 papers, 2022 to 2025). Gross necrosis of the myocardium, as a result of interruption of the blood supply to the area, as in coronary thrombosis. "The existence of NRP1+ macrophages enhance the inflammation of the coronary vessels, increasing cardiovascular risk and myocardial infarction." (PMID 38541641, 2024).
psoriasis (4 papers, 2021 to 2025). An autoimmune condition characterized by red, well-delineated plaques with silvery scales that are usually on the extensor surfaces and scalp. "Conditional loss of VEGFR-1/Flt1 or neuropilin-1 (Nrp1) in epidermal cells can reverse the psoriasis-like phenotype of VEGFA overexpressing mice, suggesting the role of blocking the VEGFA/Flt1/Nrp1 axis in psoriasis." (PMID 38203230, 2023). "Keratinocyte-specific deletion of Flt1 or Nrp1 diminished VEGFA-induced psoriasis, suggesting that VEGFA/Flt1/Nrp1 axis has an essential epidermal autonomous function in the pathogenesis of psoriasis." (PMID 35075118, 2022). "In a mouse model of psoriasis, conditional deletion of VEGFR1 or neuropilin 1 (a VEGFA co-receptor amplifying VEGFA signaling in epidermal cells) inhibits psoriasis triggered by VEGF-A overexpression." (PMID 34769465, 2021).
renal fibrosis (4 papers, 2021 to 2026). A final common manifestation of a wide variety of chronic kidney diseases characterized by glomerulosclerosis and tubulointerstitial fibrosis. "Recently, studies have revealed the mechanism of neuropilin-1 (Nrp1) regulating renal injury and renal fibrosis." (PMID 39606030, 2024). "Here, we found that Nrp1 + DT cells express cell death-related genes and pro-fibrotic factors, indicating that Nrp1 + DT cell death promotes renal fibrosis." (PMID 38977708, 2024). "Taken together, we propose that the activated Nrp1 + TECs communicate with myofibroblasts to form a vicious cycle to promote renal fibrosis." (PMID 38977708, 2024). "Meanwhile, we further confirmed that the communication between Nrp1 + DT and myofibroblasts establishes a vicious cycle of mutual activation through reciprocal secretion of pro-fibrotic factors, accelerating renal fibrosis." (PMID 38977708, 2024). "Knockout of Nrp1 in DT improved IR-induced renal injury and subsequent renal fibrosis." (PMID 38977708, 2024). "However, as a co-receptor of TGFR1, the precise relationship between NRP1 and renal fibrosis remains elusive." (PMID 38977708, 2024). "Through the construction of genetically modified mice and in vitro experiments, we demonstrated that deletion of Nrp1 or simultaneous deletion of the genes encoding the TGF-β receptor and Nrp1 delay the progression of renal fibrosis and inhibit Smad3 expression." (PMID 38977708, 2024). "Its expression in renal TECs promotes fibrosis not only by activating the canonical TGF-β-related fibrosis pathway, but also by activating a TNF-α related pathway, and Nrp1’s expression in myofibroblasts and pericytes also promotes the progression of renal fibrosis." (PMID 38977708, 2024). "However, a previous study showed a low density of NRP1 expression and downregulated NRP1 levels in renal fibrosis, which is contradictory to our findings." (PMID 33968963, 2021). "Blockade of Nrp1 and the TGF-β receptor in distal tubules significantly improved renal injury and renal fibrosis, which present a therapeutic target for addressing AKI and its progression to CKD." (PMID 38977708, 2024). "Furthermore, by single-cell RNA-sequencing we find that Nrp1-positive DT cells secrete collagen and communicate with myofibroblasts, exacerbating acute kidney injury (AKI)-induced renal fibrosis by activating Smad3." (PMID 38977708, 2024).
acute kidney injury (3 papers, 2024). Sudden and sustained deterioration of the kidney function characterized by decreased glomerular filtration rate, increased serum creatinine or oliguria. "Additionally, NRP-1 has been associated with acute renal failure by driving the accumulation of miR-21a-3p in renal tubular epithelial cells, which leads to metabolic dysfunction." (PMID 39518917, 2024). "Some studies suggest that NRP-1 worsens acute kidney injury by promoting fibrosis through the downregulation of Cox4il enzyme crotonylation and activation of Smad3." (PMID 39518917, 2024). "Furthermore, NRP-1 has been found to play a role in the inflammatory response in acute kidney injury in a mouse model." (PMID 38791476, 2024).
adenoma (3 papers, 2011 to 2022). A neoplasm arising from the epithelium. "Adenomas showed extensive, weaker staining for NRP-1 which contrastingly correlated positively with butyrate level." (PMID 21401950, 2011). "In contrast with the NRP-1 staining pattern which altered markedly in adenoma by comparison with normal tissue, the CgA staining remained limited to singly dispersed cells." (PMID 21401950, 2011). "In CRC, NRP1 expression increased significantly across the adenoma-carcinoma sequence." (PMID 31586988, 2019). "Furthermore, as NRP-1 expression is limited in the normal mucosa and is widespread in cancer tissue, we sought to investigate the expression profile of NRP-1 in adenoma and in fields around adenoma to map the onset of NRP-1 dysregulation." (PMID 21401950, 2011). "Interestingly, under conditions of low butyrate the percentage of NRP-1 expressing cells is significantly lower in the adenoma field compared to the landmark samples (p = 0.003)." (PMID 21401950, 2011). "Our data examining the expression pattern of NRP-1 and CgA in adenomas show that, whereas there are similarities and overlaps in morphologically normal tissue, the regulation of the two markers becomes profoundly unlinked in adenomas." (PMID 21401950, 2011). "Taken together these data suggest that NRP-1 expression is altered in adenomas and may be up-regulated by butyrate." (PMID 21401950, 2011). "Adenoma tissue shows dissociation of the co-regulation of NRP-1 and EEC." (PMID 21401950, 2011). "Both NRP-1 and EEC number decreased in relation to increasing SCFA concentrations at sites distant to the adenoma." (PMID 21401950, 2011).
apical periodontitis (3 papers, 2017 to 2021). "Combined with our results, it is highly likely that the reduction in Sema3A/Nrp1 expression was involved in the occurrence and developmental process of bone loss in apical periodontitis." (PMID 29457037, 2017). "We detected the expression patterns of Sema3A/Nrp1 at different developmental stages and their association with bone destruction in a rat model of apical periodontitis." (PMID 29457037, 2017). "In this study, we firstly investigated the expression pattern of Sema3A/Nrp1 in apical periodontitis and its correlation with bone destruction." (PMID 29457037, 2017). "Accumulating evidence has encouraged investigations on the potential roles of Sema3A/Nrp1 in apical periodontitis." (PMID 29457037, 2017). "In our study, the expression levels of Sema3A and Nrp1 were remarkably decreased in induced rat apical periodontitis as the disease progressed." (PMID 29457037, 2017). "The clinical samples obtained from apical periodontitis patients also demonstrated downregulated expression levels of Sema3A and Nrp1 in apical periodontitis compared to healthy control." (PMID 29457037, 2017). "In apical periodontitis, the expression of Sema3A is decreased, along with the reduced binding of Sema3A and Nrp1." (PMID 29457037, 2017). "This study demonstrated that Sema3A/Nrp1 expression was significantly decreased in rat apical periodontitis models as well as in apical periodontitis patients." (PMID 29457037, 2017). "Moreover, a decline in the expression of SEMA3A/NRP-1 signaling has been reported earlier in rats with periapical lesions as well as patients with apical periodontitis." (PMID 34821196, 2021). "In conclusion, decreased expression of Sema3A/Nrp1 was observed in periapical lesions and is potentially involved in the bone resorption of the periapical area, suggesting that Sema3A/Nrp1 may contribute to the pathological development of apical periodontitis." (PMID 29457037, 2017). "The reduction in Sema3A/Nrp1 expression may have a suppressive effect on the pathological severity of apical periodontitis by inhibiting osteoblasts, activating osteoclasts, and enhancing inflammation." (PMID 29457037, 2017). "In addition, clinical samples from apical periodontitis patients were obtained to analyse the expression of Sema3A/Nrp1." (PMID 29457037, 2017). "In this study, we hypothesized that the Sema3A/Nrp1 signaling axis would significantly contribute to bone resorption in apical periodontitis." (PMID 29457037, 2017). "Further elucidation of the role of Sema3A/Nrp1 in this disease may address the biological and pathological functions of Sema3A/Nrp1 and allow the development of new strategies for the treatment of apical periodontitis." (PMID 29457037, 2017). "Moreover, the imbalance in Sema3A and Nrp1 may also affect the etiology of apical periodontitis." (PMID 29457037, 2017). "In addition, we found that Sema3A/Nrp1 expression exhibits a significantly negative correlation with osteoclast formation in apical periodontitis." (PMID 29457037, 2017).
colorectal tumor (3 papers, 2010 to 2021). "We also found that metastatic foci expressed higher levels of NRP1 than primary colorectal tumor tissues." (PMID 33846300, 2021). "Notably, the abnormal NRP1 DNA fragments were found in a subset of primary colorectal tumors (NF99, NF103, NF105, NF106, NF110) and the primary CRC and liver metastasis tumor cell lines (Pt93, Pt2377 and LM2377) at an expression level equal to or above that found for NRP1-WT mRNA." (PMID 31420553, 2019).